KDM2B (lysine demethylase 2B)
Diseases named in the same sentence as KDM2B in open-access papers (continued):
Sharing a sentence is not in itself a finding about the gene and the disease.
tumor (continued). "This hypothesis was further confirmed by performing in vitro and in vivo experiments, as the proliferation, colony formation, migration and invasion of tumour cells were all enhanced by acetylation‐resistant mutant of KDM2B." (PMID 31218831, 2019). "Taken together, these results suggest that KDM2B silencing led to decreased tumor growth in long term, which may be attributable to the increased basal levels of apoptosis." (PMID 28661478, 2017). "For example, KDM2B has recently been shown being involved in tumor metabolism." (PMID 26989077, 2016). "Inhibiting KDM2B could be an option to induce host immune responses against HSA tumor cells; however, we were unable to investigate the function of KDM2B on immune responses in canine HSA because the immunodeficient mouse model was not suitable to study the immune responses." (PMID 35136176, 2022). "In conclusion, we now report that KDM2B is preferentially expressed therapeutically resistant pool of GSCs, creating a dependency for which inhibition leads to accumulation of DNA damage, which if left unrepaired induces apoptosis and significantly reduces the pool of stem‐like tumor cells." (PMID 29360266, 2018). "Immunohistochemical staining showed that the expression of the KDM2B protein was mainly located at the nucleus of CRC cells, and its expression was significantly higher in tumor tissues compared with their adjacent normal tissues (p < 0.05)." (PMID 33791221, 2021). "KDM2B expression was increased at both mRNA and protein levels in LUSC patient tumor tissues compared with their adjacent normal tissues." (PMID 34783291, 2021). "KDM2B regulates actin cytoskeleton and epithelial-to-mesenchymal transition by upregulating Rho-GTPases and activating FAK/PI3K signaling, thus promoting tumor cell motility." (PMID 33665162, 2020). "Overexpression of KDM2B and KDM5A genes plays significant roles in promoting poor differentiation and tumor proliferation in PDAC, respectively, whereas knockdown of the KDM3A gene leads to decreased invasive activities in culture and impedes the formation of orthotopic tumors in mice." (PMID 38791111, 2024). "While KDM6A and KDM6B have a tumor suppressor role, other members of the KDM family like KDM2B, KDM3A, and KDM5A may serve as oncogenes in PDAC." (PMID 38791111, 2024). "Intriguingly, KDM2B was found to activate FAK and PI3K that mediate the motility of tumor cells." (PMID 34266408, 2021). "Overall, these data also suggest that targeting EZH2 in these tumors, without targeting KDM2B may not be sufficient to inhibit tumor growth." (PMID 28515962, 2017). "Viewed in the context of the results of our earlier studies, these data suggest that the tumor phenotype may be due to the promotion of FGF-2 responsiveness by the Akt3/IWS1 pathway and the induction of EMT and stem cell self-renewal by FGF-2 via the FGF-2/KDM2B/miR-101/EZH2 pathway." (PMID 28515962, 2017).
infection (8 papers, 2019 to 2026). The state of being infected such as from the introduction of a foreign agent such as serum, vaccine, antigenic substance or organism. "As a result, we identified the Nucleosome Remodeling and Deacetylase (NuRD) complex, Tip60 and Tip60-associated co-repressors, and the histone demethylase KDM2B as inhibitors of the KSHV lytic cycle both during primary infection and in latently infected cells." (PMID 31923286, 2020). "As a result, we identified the Nucleosome Remodeling and Deacetylase (NuRD) complex, Tip60 and Tip60-associated co-repressors, and the histone demethylase KDM2B as repressors of KSHV lytic genes during both de novo infection and the maintenance of viral latency." (PMID 31923286, 2020). "The binding of KDM2B prior to PRC-regulated heterochromatin supports the potential role of KDM2B in the recruitment of PRCs to viral DNA following de novo initial infection." (PMID 32508765, 2020). "Collectively, our results show that KDM2B inhibits the lytic cycle of KSHV following de novo infection mainly by binding to the RTA promoter as early as 8 hpi and reducing the level of specific activating histone marks on it at 24 hpi." (PMID 31923286, 2020). "This non-canonical PRC1 recruitment can be mediated by transcription factors or epigenetic factors like KDM2B that can rapidly bind to the KSHV DNA during de novo infection." (PMID 31923286, 2020). "Importantly, the removal of activating histone marks, especially H3K4me3, by KDM2B can favor the downregulation of RTA expression during primary infection, which is required for the establishment of viral latency." (PMID 31923286, 2020). "Importantly, the binding of KDM2B to the viral episome at 8 hpi is consistent with its early inhibitory function at viral genes during de novo infection." (PMID 31923286, 2020). "However, in contrast to KSHV infection, EBV induces rapid downregulation of KDM2B expression in B cells following primary infection, which is accompanied by a transient enrichment of KDM2B on an EBV gene promoter at 48 hpi." (PMID 31923286, 2020). "Of these host factors, we showed that NuRD, Tip60 and its co-repressors, and KDM2B could inhibit lytic genes both following primary infection and during latency in different cell types." (PMID 31923286, 2020). "The fact that KDM2B can bind to the viral episome in latency and can inhibit lytic gene expression a few hours after KSHV infection suggests that KDM2B may rapidly bind to the viral genome during de novo infection." (PMID 31923286, 2020). "Thus, we propose that KDM2B is a crucial host restriction factor that limits the level of activating histone marks on the viral chromatin during de novo infection to block full-scale lytic gene expression in the early phase of infection when heterochromatin is not yet established on the lytic genes." (PMID 31923286, 2020). "Based on the diverse functions of KDM2B, NuRD and Tip60-R they can potentially inhibit the lytic cycle of KSHV following de novo infection by contributing to the different epigenetic layers of the KSHV epigenome." (PMID 31923286, 2020). "Since both KDM2B and LANA can bind to the viral episome within hours of infection, we wanted to determine if LANA is involved in the recruitment of KDM2B to the viral DNA." (PMID 31923286, 2020). "KDM2B has been demonstrated to bind to unmethylated CpG islands on DNA, and since KSHV DNA is largely unmethylated during de novo infection, the viral genome is an excellent target for KDM2B." (PMID 31923286, 2020). "We found that KDM2B rapidly binds to the viral episome as early as 8 hpi during de novo KSHV infection and repress lytic gene expression in the first 24 hours of infection." (PMID 31923286, 2020). "HDAC5, KDM2B, EZH1, PRDM2, SETMAR, SMYD4 and USP12 were differentially expressed at all time points post-infection (excluding 2 hpi)." (PMID 30728374, 2019).
infection (continued). "In summary, following de novo infection, the KSHV IE protein K-Rta may help viral episomes acquire active histone marks and cellular factors such as KDM2B may function to limit the enrichment of active histone marks." (PMID 32508765, 2020). "CD8+ TRM failed to accumulate the following infection in the absence of Kdm2b." (PMID 36156073, 2022). "Therefore, we hypothesized that KDM2B, NuRD, and Tip60-R can also play a role in the inhibition of lytic KSHV genes not only during primary infection but also during latency." (PMID 31923286, 2020). "To further demonstrate that KDM2B can control the level of activating histone marks on the RTA promoter, we also tested whether the overexpression of KDM2B affects the level of H3K4me3 on the KSHV genome during primary infection." (PMID 31923286, 2020). "To test if KDM2B can regulate the enrichment of any of the activating histone marks on the viral episome during de novo KSHV infection, we performed histone mark ChIPs on the RTA, K2, and ORF25 viral genes in shKDM2B-treated SLK cells following 24 hours post-infection." (PMID 31923286, 2020). "In contrast, while shKDM2B resulted in reduced binding of RING1B on the Myc promoter, which is a known target of KDM2B, we could not detect any significant changes in RING1B enrichment in most parts of the RTA locus during KSHV de novo infection." (PMID 31923286, 2020). "However, our recent study showed that KDM2B is not involved in recruiting PRC1 to KSHV lytic promoters and here we found that it also does not control RYBP binding to viral lytic promoters during de novo infection." (PMID 36026503, 2022).
neurodevelopmental disorder (5 papers, 2023 to 2026). A behavioral and cognitive disorder with onset during the developmental period that involves impaired or aberrant development of intellectual, motor, or social functions. "Rare variants affecting the epigenetic regulator KDM2B cause a recently delineated neurodevelopmental disorder." (PMID 40420380, 2025). "Our findings suggest KDM2B CxxC variants are associated with a distinct neurodevelopmental disorder possibly through a dominant-negative mechanism as opposed to haploinsufficiency associated with loss-of-function variants." (PMID 40420380, 2025). "Heterozygous variants in KDM2B were recently associated with a neurodevelopmental disorder." (PMID 41946911, 2026).
hematologic malignancies (2 papers, 2017 to 2021). "In fact, both upregulation and downregulation of the expression of KDM2B have been observed in different hematologic malignancies and its role can differ depending on the specific cell type." (PMID 34204821, 2021). "Last, it is worth noting that aberrant activity of KDM2B, which catalyzes the demethylation of H3K36me2, has also been observed in hematologic malignancies, further illustrating the critical significance of tight regulation of this modification for hematopoietic cell homeostasis." (PMID 34204821, 2021). "We then focused on KDM2B, as its protumorigenic functions have been demonstrated in various solid and hematological malignancies;21, 22 however, its function in GBMs was not defined." (PMID 28661478, 2017).
bacterial infection (1 paper, 2021). "The expression of KDM2B has been shown to help maintain ILC3 cells, while reduction in ILC3s leads to susceptibility to bacterial infection." (PMID 34252097, 2021).
neurodegenerative disease (1 paper, 2024). A disorder of the central nervous system characterized by gradual and progressive loss of neural tissue and neurologic function. "Regarding neurodegenerative diseases, the HDMs KDM2A and KDM2B were shown to play a role in AD." (PMID 39765675, 2024).
KDM2B also shares sentences with these, for which no sentence is quoted: gastric cancer (6 papers); Hypertension (2); Intellectual disability (2); Microdeletion Syndrome (2); neurological disorder (2); adenocarcinoma (1); attention deficit-hyperactivity disorder (1); B-cell acute lymphoblastic leukemia (1); brain tumors (1); cardiomyopathy (1); Cerebral ischemia (1); chondrosarcoma (1); depression (1); diabetic cardiomyopathy (1); dysplasia (1); epilepsy (1); focal epilepsy (1); follicular lymphoma (1); gynecological tumors (1); hepatocellular carcinoma (1); Hutchinson-Gilford progeria syndrome (1); Hyperglycemia (1); lactic acidosis (1); lung adenocarcinoma (1); lymphoma (1); macroglossia (1); myelodysplastic syndrome (1); myopathy (1); progeria (1); sideroblastic anemia 2 (1).
A further 5 diseases each share a sentence with KDM2B in 1 paper.